NLRX1 (NLR family member X1)
Description:
Participates in antiviral signaling. Acts as a negative regulator of MAVS-mediated antiviral responses, through the inhibition of the virus-induced RLH (RIG-like helicase)-MAVS interaction. Instead, promotes autophagy by interacting with TUFM and subsequently recruiting the autophagy-related proteins ATG5 and ATG12. Also regulates MAVS-dependent NLRP3 inflammasome activation to attenuate apoptosis. Has no inhibitory function on NF-kappa-B signaling pathway, but enhances NF-kappa-B and JUN N-terminal kinase dependent signaling through the production of reactive oxygen species. Regulates viral mediated-inflammation and energy metabolism in a sex-dependent manner (By similarity). In females, prevents uncontrolled inflammation and energy metabolism and thus, may contribute to the sex differences observed in infectious and inflammatory diseases (By similarity).
Synonyms: CLR11.3; NOD5; NOD9; DLNB26; NOD26
Tractability: Antibody: its Gene Ontology location is reachable by antibodies, with high confidence. PROTAC: its protein half-life has been measured.
Gene: Protein-coding gene on chromosome 11 (119,166,481 to 119,184,017, forward strand). Ensembl gene ENSG00000160703.
Subcellular location: Mitochondrion outer membrane
Subcellular location (Human Protein Atlas): Mitochondria; Plasma membrane
Pathways (Reactome):
Immune System: DDX58/IFIH1-mediated induction of interferon-alpha/beta; Negative regulators of DDX58/IFIH1 signaling; Regulation of NF-kappa B signaling
Gene Ontology:
Molecular function: protein binding
Biological process: negative regulation of canonical NF-kappaB signal transduction; negative regulation of RIG-I signaling pathway
Cellular component: mitochondrial outer membrane; mitochondrion; cytosol
Genetic constraint (gnomAD): Loss-of-function variants: 65 observed, 73.67 expected, observed/expected ratio (o/e) 0.88, 90% interval 0.72 to 1.09. The upper end of that interval is the gene's LOEUF score, 1.09, which puts it in group 4 of 6, group 1 being the genes least tolerant of losing a copy. Missense variants: 1,178 observed, 1,351.9 expected, observed/expected ratio (o/e) 0.87, 90% interval 0.83 to 0.91. Synonymous variants: 504 observed, 582.95 expected, observed/expected ratio (o/e) 0.86, 90% interval 0.8 to 0.93.
Homologues: Orthologues: chimpanzee NLRX1 (99% identical), macaque NLRX1 (96% identical), pig NLRX1 (92% identical), mouse Nlrx1 (90% identical), dog NLRX1 (90% identical), rat Nlrx1 (90% identical), guinea pig NLRX1 (89% identical), rabbit NLRX1 (73% identical), tropical clawed frog nlrx1 (52% identical), zebrafish nlrx1 (43% identical). Paralogues in human: NLRP1 (19% identical), NLRP12 (17% identical), NLRP3 (17% identical), NLRP7 (17% identical), NLRC3 (17% identical), NLRP2 (17% identical), NLRP4 (16% identical), NLRP14 (15% identical), NLRP5 (15% identical), NLRC5 (15% identical), NLRP13 (15% identical), NLRP9 (15% identical), and 8 more.
Diseases named in the same sentence as NLRX1 in open-access papers:
NLRX1 is named in the same sentence as 85 diseases in open-access papers, as found by Europe PMC text mining. Sharing a sentence is not in itself a finding about the gene and the disease. The quoted sentences say what the papers report.
viral infection (25 papers, 2014 to 2025). "In MEFs from Nlrx1-/- mice, increased levels of phosphorylated TBK1 were observed following virus infection, which was shown to be associated with NLRX1 inhibition of the STING pathway." (PMID 40356929, 2025). "By negatively regulating antiviral immune responses, NLRX1 not only makes the host susceptible to viral infections but promotes virus-induced tumor development (e.g., Kaposi’s sarcoma or primary effusion lymphoma) as well." (PMID 33525671, 2021). "Previous research implicated Nlrx1 in the regulation of autophagy and reactive oxygen species production during viral infection." (PMID 25540124, 2014). "In alveolar macrophages, the interaction of NLRX1 with PB1-F2 was observed to be localized to the mitochondria following virus infection." (PMID 40356929, 2025). "Nucleotide-binding oligomerization domain-like receptor X1 (NLRX1), another mitochondrial outer membrane protein, is known as a negative regulator of the innate immune response to viral infection." (PMID 40162781, 2025). "In this review we will discuss the multifaceted role NLRX1 plays in modulating the fine-tuned host immune response during viral infection." (PMID 40356929, 2025). "By synthesizing current research, this review provides insight into how NLRX1 regulates immune signaling in RNA and DNA viral infections, highlighting its dynamic role in antiviral immunity and the remaining gaps in our understanding." (PMID 40356929, 2025). "Specifically in cancers influenced by viral infections, the ability of NLRX1 to inhibit mitochondrial interferon signaling suggests this function of NLRX1 can be detrimental to the host." (PMID 37342194, 2023). "The exact mechanism for microbial responses following NLRX1 activation has been studied extensively in viral work where NLRX1 attenuates Type 1 Interferon production and induces autophagy following viral infection." (PMID 35572547, 2022). "For example, TUFM is known to mediate autophagy by interacting with the mitochondrial protein NLRX1 upon virus infection." (PMID 34511600, 2022). "Accordingly, virus infection causes higher expression of IFNa2, IFNb1, OAS1, and STAT2 in Nlrx1−/− mice when compared to wild-type mice." (PMID 33525590, 2021). "Knockdown of NLRX1 leads to enhanced transcription levels of IFNb1, STAT2, and the 2′-5′-oligoadenylate synthetase 1 gene (OAS1) after viral infection, suggesting a negative regulatory role of NLRX1 on the IFN-β/STAT2/OAS1 axis." (PMID 33525590, 2021). "Some research groups found no changes, whereas others published a negative regulatory role of NLRX1 in MAVS-dependent type I IFN production of MEFs as a response to viral infection." (PMID 33525671, 2021). "The same research group described that the mitochondrial NLRX1-TUFM complex not only has a role during viral infection but also promotes autophagy and survival of tumor cells." (PMID 33525671, 2021). "In contrast to viral infection, it was also observed that NLRX1 negatively regulates autophagy upon bacterial infections caused by Group A Streptococcus (GAS)." (PMID 33525671, 2021). "Specifically, NLRX1 attenuated type I IFN production while promoting autophagy during viral infection." (PMID 32316236, 2020). "NLRX1 functions as an anti-inflammatory NLR in various disease models such as viral infection, cancer and multiple sclerosis." (PMID 33362773, 2020). "Recent mouse studies have shown that NLRX1 significantly impacts a multitude of diseases, including cancer, virus infection, osteoarthritis, traumatic brain injury, and inflammatory bowel disease." (PMID 31681307, 2019). "On the other hand, direct association of NLRX1 with MAVS and STING inhibits MAVS-RLR pathway and STING-TBK1 signaling, respectively, thereby suppresses type I IFN response and promotes viral infection." (PMID 30559741, 2018).
viral infection (continued). "Through association with different partners, NLRX1 acts as a negative regulator to inhibit TLR, MAVS, and STING pathways, and as a positive regulator to facilitate autophagy in response to viral infection." (PMID 30559741, 2018). "This supports our time course binding studies, which showed that FAF1 binds to NLRX1 at early time points (2 and/or 4 hpi) after virus infection." (PMID 28542569, 2017). "In the context of viral infections, NLRX1 acts as a negative regulator of the antiviral signaling pathway." (PMID 29403486, 2017). "It has been demonstrated that the interaction between NLRX1 and viral components might be a key factor in determining the outcome of viral infections." (PMID 38891045, 2024). "Hence, the NLRX1-MAVS interaction weakens the cytokine response to viral infections and prevents an overzealous immune response." (PMID 38003837, 2023). "Recent reports suggest that the immune modulator NLR containing X1 (NLRX1) may sequester STING during viral infection." (PMID 35283725, 2022). "The NLRX1 may be a crucial protein for antagonizing a viral infection through autophagy, but this has yet to be validated." (PMID 35891364, 2022). "Furthermore, NLRX1 also promotes autophagy through association with Tu translation elongation factor (TUFM) and enhances IRF1 protein levels upon viral infection by attenuating the inhibition of mRNA translation by protein kinase R (PKR)." (PMID 33525590, 2021). "In addition to interactions with TUFM during virus infection, NLRX1 has also been shown to modulate autophagy though interactions with the Beclin 1-UVRAG complex." (PMID 31681307, 2019). "In ER/PR- human breast cancer, which also is not driven by viral infections, NLRX1 enhanced aggressive in vitro cancer-associated phenotypes through augmenting mitochondrial respiration and reducing mitophagy and lysosomal formation and function through mitochondria-lysosomal crosstalk." (PMID 37342194, 2023). "However, the mechanism that regulates NLRX1 during virus infection remains poorly characterized." (PMID 28542569, 2017). "NLRX1 negatively regulates MAVS-mediated IRF3 activation and type I IFN induction during viral infection." (PMID 41463370, 2025). "In vitro studies have shown that NLRX1, a mitochondrial PAMP, increases during viral infections, such as human immunodeficiency virus type 1 (HIV-1), resulting in increased oxidative phosphorylation and glycolysis." (PMID 39872813, 2025). "NLRX1 negatively regulates multiple inflammatory signaling pathways, including RIG-I and NF-κB signaling, during viral infections to facilitate inflammation resolution and maintain immune system homeostasis." (PMID 40356929, 2025). "NLRX1, a modulator of PAMP receptors, is generally considered a negative regulator of the innate immune response to viral infections (25, 58, –, 62)." (PMID 40162781, 2025). "In epithelial-like HEK293T and HeLa cells, NLRX1 acts as a negative regulator of RLR-mediated antiviral signaling, as it decreases type I IFN production following viral infection via interacting with the adaptor protein MAVS and inhibiting IRF3 dimerization." (PMID 33525671, 2021). "All these data demonstrate that NLRX1 and NLRC5 can control the type I IFN and pro-inflammatory responses to live virus infection of human DCs as well." (PMID 30344524, 2018). "We also examined the time course binding of NLRX1 and MAVS and compared it with that of NLRX1 and FAF1 after the virus infection." (PMID 28542569, 2017). "However, in the NLR family, there are members of great importance for inflammatory functions such as NLRP3 or NLRX1, which regulatory functions on RIG-I/MAVS pathway and are important in viral infection, and NOD2, a less studied effector in viral infections." (PMID 38668261, 2024). "Our current study did not indicate a significant role of NLRX1 in mitochondrial interferon signaling in Pan02 cells, which is not surprising as pancreatic cancer is not typically driven by viral infections." (PMID 37342194, 2023).
viral infection (continued). "Thus, NLRX1 helps to maintain IRF1 upregulation, while inhibits IRF3 dimerization upon viral infection." (PMID 33525671, 2021). "Several molecules like NLRX1 and DUBs regulate RIG-I binding to MAVS at the mitochondria or directly target MAVS for degradation, thus acting as a counterbalance to prevent overproduction of Type I Interferons during a persistent viral infection." (PMID 32983015, 2020). "Similar to previous studies showing constitutive interaction between RIG-I and MAVS in NLRX1-deficient cells, we found that NLRX1 bound to MAVS in the absence of virus infection." (PMID 28542569, 2017). "However, during virus infection, the mechanism which controls type I interferon (IFN) signaling via modulating the MAVS and NLRX1 interaction, needs to be investigated more in detail." (PMID 28542569, 2017). "However, after virus infection, FAF1 appears to displace MAVS from NLRX1 by competitive binding to NLRX1." (PMID 28542569, 2017). "Our work suggests that in the absence of viral infection, Nlrx1 redirects cellular stress towards apoptosis thus, protecting cells from necrosis-like cell death." (PMID 25540124, 2014). "NLRX1 is known to function as a negative NLR, attenuating the inflammatory response to bacterial or viral infection." (PMID 33362773, 2020).
colitis (16 papers, 2014 to 2024). Inflammation of the colon. "Loss of function of NLRX1 has been linked with a variety of autoimmune diseases, such as cancer, colitis, inflammatory bowel disease and CNS inflammation." (PMID 33682108, 2021). "Leber at al. described that NLRX1 deficient mice with DSS-induced colitis represent more severe inflammation and disease pathology with enhanced intestinal expression of neutrophil-attracting chemokines, pro-inflammatory cytokines and antimicrobial peptides." (PMID 33525671, 2021). "Recently, NLRX1 deficient mice have been studied in colitis 19 and EAE models 20, which are T cell-mediated diseases." (PMID 32194859, 2020). "NLRX1 deficient mice showed more severe colitis and EAE than WT mice with increased T cell infiltration and inflammatory cytokines." (PMID 32194859, 2020). "Cell-specificity studies using cre-lox mice demonstrate that the loss of NLRX1 in intestinal epithelial cells (IEC) recapitulate the increased sensitivity to DSS colitis observed in whole body Nlrx1−/− mice." (PMID 29535731, 2018). "The Nlrx1−/− mice were also found to have increased colon inflammation associated with DSS exposure." (PMID 27105514, 2016). "RNA-seq data from colons of wild-type and NLRX1-/- mice with colitis demonstrates that NLRX1 regulates the expression of genes associated with lipid metabolism, thereby suggesting a link between lipid molecules and NLRX1 activity." (PMID 26714018, 2015). "In contrast, in a colitis-associated cancer model combining azoxymethane and dextran sulfate sodium, NLRX1−/− mice developed a more severe pathology likely due to the increased sensitivity to dextran sulfate sodium colitis." (PMID 24867956, 2014). "The increased susceptibility of NLRX1−/− mice to AOM/DSS colitis is thus likely the consequence of an exacerbated rate of apoptotic cell death in response to DSS treatment followed by increased epithelial proliferation." (PMID 24867956, 2014). "Our results have shown that NLRX1−/− mice are more susceptible to DSS colitis than WT mice and display enhanced intestinal injury and apoptosis even in the absence of a pretreatment with AOM." (PMID 24867956, 2014). "The loss of NLRX1 in small intestinal epithelial cells (IECs) leads to higher sensitivity to DSS-induced colitis, which could be a result of a gut microbiome imbalance." (PMID 37833958, 2023). "NLRX1 deficiency resulted in enhanced disease pathology in DSS-induced colitis." (PMID 33525671, 2021). "When mice were challenged with 3% DSS in drinking water to induce acute colitis, we first observed that NLRX1−/− mice exhibited increased susceptibility as evidenced by histopathological analysis and quantification of fecal lipocalin-2, a marker of colitis." (PMID 24867956, 2014). "NX-13 activation of NLRX1 reduces intracellular reactive oxygen species and decreases inflammation in animal models of colitis." (PMID 37952114, 2024). "In CD4+ T cells, NLRX1 deficiency decreased OXPHOS and led to Th17 and Th1 differentiation by promoting aerobic glycolysis in models of colitis induced by dextran sodium sulfate (DSS)." (PMID 37574163, 2023). "While the gut microbiome of NLRX1- and NLRP12-deficient mice have been evaluated in the context of colitis, their potential predisposition towards GFD has yet to be meaningfully demonstrated." (PMID 35572547, 2022). "NLRX1 has been previously demonstrated as a key regulator in maintaining host-gut microbiota interactions and protecting against gut dysbiosis in colitis." (PMID 35572547, 2022). "The emergence of NLRX1 agonists such as NX‐13 show the potential in targeting NLRX1 to modulate immunometabolic function in diease, and future research focusing on its involvement in colitis and gut microbiota is needed." (PMID 33682108, 2021).
colitis (continued). "As such, we identify through both oral supplementation with glutamine and inhibition of its use by the host effectively restore the Nlrx1−/−-associated gut microbiome and resolve differences in disease severity and immune response during DSS colitis." (PMID 29535731, 2018). "The NLRX1 dependent anti-inflammatory efficacy of PUA was further validated in the DSS-induced colitis model." (PMID 26714018, 2015). "Next, in a model of AOM/DSS-induced carcinogenesis, we obtained results that were in line with DSS colitis experiments: NLRX1−/− mice displayed increased number of polyps than WT mice, in particular large tumors (>2 mm)." (PMID 24867956, 2014). "On the other hand, Nlrx1-deficiency led to increased expression of wound healing factors epidermal growth factor (EGF) and TGFβ in epithelial cells in a mouse model of DSS-induced colitis." (PMID 35651602, 2022). "Similarly, in Citrobacter rodentium-induced colitis, T cell—specific deletion of NLRX1 resulted in greater inflammation." (PMID 33525671, 2021). "Another study showed that NLRX1 deletion in colitis mice drives changes in gut–microbiome interactions exacerbating disease; however, restoration of WT glutamine metabolic profiles via glutamine supplementation abrogated effects in microbiome, inflammation and disease severity." (PMID 33682108, 2021). "The T-cell intrinsic role of NLRX1 was confirmed in adoptive-transfer model of colitis." (PMID 29403486, 2017). "The NLRX1-dependent mechanism of PUA was further confirmed in the DSS model of colitis." (PMID 29403486, 2017). "Our findings showed that the regulatory function of PUA on colitis is NLRX1 dependent." (PMID 26714018, 2015). "Indeed, NLRX1 reduced tumor progression in colitis and sarcoma models." (PMID 37574163, 2023). "Interestingly, NLRX1 is also expressed by CD4+ T cells, and the loss of NLRX1 results in increased disease severity and increased numbers of Th1 and Th17 cells producing inflammatory cytokines (IFN-γ, TNF, and IL-17) in dextran sodium sulfate-induced (DSS) colitis." (PMID 34697412, 2022). "Leber at al. investigated the role of NLRX1 in three different mouse models of IBD including cellular-, dextran sodium sulfate (DSS)-, and Citrobacter rodentium-induced colitis." (PMID 33525671, 2021). "The anti-inflammatory effect of PUA was mediated through NLRX1, which was further confirmed in a DSS-induced colitis model, where PUA alleviated symptoms of wild type animals, but did not reduce colitis symptoms of NLRX1-KO mice." (PMID 33525671, 2021). "Through analysis of an RNA-seq dataset encompassing Nlrx1-/- and wild type mice challenged with a dextran sodium sulfate (DSS) model of colitis, we observed a significant dysregulation of lipid metabolism associated genes." (PMID 26714018, 2015). "In contrast, PUA treatment did not ameliorate experimental colitis in Nlrx1−/− mice compared to wild-type mice." (PMID 34697412, 2022). "Members of the Veillonellaceae family are associated with many chronic inflammatory diseases, including IBD, and its abundance was increased in NLR family member x1 (Nlrx1) knockout mice and WT mice CoHo with Nlrx1−/− mice, which worsened the DSS-induced colitis." (PMID 36175956, 2022). "In dextran sodium sulfate-induced colitis mouse model, lack of NLRX1 results in enhanced TH1- and TH17-related inflammatory cytokines, such as IFN-γ, TNF-α, and IL-17, and consequently increased the severity of the disease." (PMID 29403486, 2017). "Mice were observed daily for disease activity with WT mice given PUA showing significant symptom regulation, while Nlrx1-/- counterparts had no observable inhibition of colitis." (PMID 26714018, 2015).